IL1B (interleukin 1 beta)
Diseases named in the same sentence as IL1B in open-access papers (continued):
Sharing a sentence is not in itself a finding about the gene and the disease.
Glucose intolerance (25 papers, 2014 to 2025). Glucose intolerance (GI) can be defined as dysglycemia that comprises both prediabetes and diabetes. "Treatments with either Cxcl1 or IL-1β restored the mature β cell phenotype and rescued MyD88-deficient mice from glucose intolerance, indicating the Cxcl1/IL-1β axis as a potential therapeutic target." (PMID 38885342, 2024). "Fecal Bifidobacteria levels were inversely associated with glucose intolerance and inflammatory biomarkers, including IL-1β, IL-6, TNF-α and MCP-1." (PMID 33922965, 2021). "hIAPP has been shown to drive pancreatic islet β-cell death through the secretion of proinflammatory cytokines by macrophages, particularly IL-1β, causing islet dysfunction and ultimately glucose intolerance." (PMID 32229246, 2020). "The role of NLRP3 signaling was also confirmed in vivo as deletion of NLRP3 or anti-IL-1β treatment reversed the pro-inflammatory milieu in the gut, insulin secretion defect and glucose intolerance." (PMID 37400850, 2023). "Taken together, DEP-induced gut inflammation and glucose intolerance were reversed by pharmacological inhibition of IL-1β." (PMID 37400850, 2023). "Depletion of macrophages, NLRP3 or IL-1β protected mice from air pollution-induced glucose intolerance." (PMID 37400850, 2023). "Compared with the WT HFD mice, GSDMD KO HFD mice exhibited a mild increase in HFD-induced glucose intolerance with increased systemic and adipose tissue IL-1β levels." (PMID 36065376, 2022). "In this context, blockade of IL-1β has been shown to ameliorate amyloid-induced glucose intolerance and islet inflammation and to increase β-cell survival after islet transplantation." (PMID 32229246, 2020). "In addition, K6 probiotics significantly mitigated SD-induced weight loss, exercise performance decrement, glucose intolerance, inflammation (TNF-α, IL-1β), tight junction hyperpermeability (Claudin-1, ZO-1), and circadian dysregulation (BMAL-1, CLOCK)." (PMID 40959574, 2025). "Next, we tested the potential contribution of IL-1β to glucose intolerance in the ΔMyD88Peri mice." (PMID 38885342, 2024). "Thus, lower levels of IL-1β in ΔMyD88Peri mice likely contributed to β cell failure and glucose intolerance." (PMID 38885342, 2024). "Lastly, we assessed whether the involvement of NLRP3 in air pollution-induced glucose intolerance was mediated by the secretion of IL-1β as a potential target for a therapeutic intervention." (PMID 37400850, 2023). "For T2D, one previous study had indicated IL-1β could impair insulin secretion, contributing to the development of glucose intolerance and T2D." (PMID 37113481, 2023). "HF diet resulted in the greatest weight gain, adiposity, and glucose intolerance in 3xTg-AD females, which were associated with markedly increased hypothalamic expression of GFAP and IL-1β, as well as GFAP labeling in several hypothalamic nuclei that regulate energy balance." (PMID 32993686, 2020). "PAR4-/- mice developed less visceral adiposity and glucose intolerance under HFD, featuring smaller adipocytes, fewer macrophages and lower expression of adipogenic (leptin, PPARγ) and pro-inflammatory genes (CCL2, IL-1β) in WAT." (PMID 38652276, 2024). "Accordingly, we noted that doxepin treatment led to increases in serum CRP, IL-1β, and TNF-α levels in our doxepin-treated mice, in parallel with glucose intolerance exacerbation." (PMID 33809508, 2021). "Glucose intolerance was partially prevented by L. kefiri treatment (GTT) and local inflammation (TNFα; IL1β; IL6 and INFγ) was completely inhibited in EAT." (PMID 28513533, 2017).
head and neck cancer (25 papers, 1993 to 2025). A primary or metastatic malignant neoplasm affecting the head and neck. "In advanced NSCLC, high IL-1β levels were identified as an adverse prognostic factor associated with shorter progression-free and OS, while in head and neck cancer elevated IL-1α correlated with an increased risk of distant metastasis." (PMID 41465261, 2025). "The study aimed to evaluate the relationship of IL-1B/IL-1RN polymorphisms to the predisposition of head and neck cancer (HNC) in a Chinese Han population." (PMID 33472637, 2021). "A previous study that detected salivary cytokines in patients with head and neck cancer with concurrent CTx and RT reported a significant increase in the salivary levels of IL-1β, IL-6, and TNF, that were all positively associated with the mucosal toxicity severity." (PMID 35476641, 2022). "Additionally, IL-1β is involved in cytokine production, cancer metastasis, and angiogenesis, and its overexpression is associated with poor outcomes in colorectal, lung, breast, and head and neck cancers." (PMID 40002076, 2025). "Suppression of CD147 diminishing IL-1β, IL-6, and IL-8 production was previously demonstrated in head and neck cancer." (PMID 34948304, 2021). "IL1B is an inflammatory cytokine gene and acts as a therapeutic target for the treatment of head and neck cancer." (PMID 34986125, 2021). "In a recent study on a cohort of 32 patients with head and neck cancer treated with chemoradiotherapy IL-1β and TNF-α levels decreased 60 days after treatment as compared to the pre-treatment level whereas IL-6 levels increased." (PMID 31750257, 2019). "Although macrophages are known to be the major cells secreting IL-1β in tumor microenvironment, tumor cells such as prostate, breast, and head & neck cancer cells are also able to produce IL-1β to potentiate their progression and invasiveness." (PMID 27487154, 2016). "Mean value levels (ng/ml) of Interleukin 1-beta (IL-1β), Interleukin 6 (IL-6), and Interleukin 10 (IL-10) before treatment, 7 weeks after the start of treatment, 3 and 12 months after the termination of treatment in patients with head and neck cancer." (PMID 31750257, 2019). "In a study by that longitudinally evaluated the saliva of patients with head and neck cancer undergoing treatment with RT and CRT, was showed an increase in cytokines IL-1β, IL-6 and TNFα in the saliva of patients who underwent CRT compared to RT." (PMID 38725825, 2024). "The head and neck carcinoma group had significantly higher concentrations of IL-8, TNF, and VEGF in the pre-index group, and IL-1β and TNF in the post-index group." (PMID 35476641, 2022). "In head and neck cancer, the inhibition of CD147 alleviates proinflammatory cytokines, e.g., IL-1β, IL-6, and IL-8, mediated cancer cell proliferation in vitro and in vivo." (PMID 34948304, 2021). "In this study, we analyzed the immune regulatory properties of EGFR signaling in head and neck cancer cells and showed that it suppresses type 1 cytokine-induced expression of CCL2, CCL5, CXCL9, CXCL10 and IL-6 while promoting the expression of IL-1β." (PMID 30192802, 2018). "Our data have also shown increased mRNA level of pro-inflammatory cytokines such as Il1a, Il1b, Tnf, Ptgs2 in mouse ASCC as compared with control anal skin, which is well demonstrated in human and mice head and neck cancer." (PMID 24124460, 2013). "The head and neck cancer patients’ salivary cytokines that were assessed by the studies, along with photobiomodulation therapy, included IL-12p70, TNF-α, IL-6, IL-8, IL-10, CXCL8, and IL-1β." (PMID 38792366, 2024). "Induction of IFNβ post-IR followed by the interplay of IFN-induced proteins (STAT1, ISG15) and cytokines (IL-1β, IL-6, MIF) hints towards IR-induced inflammation contributing to initiation and progression of oral mucositis that affects a majority of head and neck cancer patients." (PMID 37384298, 2023).
head and neck cancer (continued). "Indeed, the other researchers had assessed the presence of salivary cytokines (e.g., IFN-γ, IL-1β, IL-6, IL-8, IL-10, TNF-α, VEGF) in patients with head and neck cancer (HNC)." (PMID 29515773, 2018). "The enhanced expression of IL-1β after GW5074 treatment was related to an increased phosphorylation of MEK1 and ERK1/2, indirectly confirming that activation of EGFR-downstream MEK and ERK affect IFNγ/TNFα induced chemokine secretion in head and neck cancer." (PMID 30192802, 2018).
inflammatory skin disease (25 papers, 2010 to 2025). Inflammatory skin disorders covers a broad category that includes many conditions ranging in severity, from mild itching to grave medical health complications These disorders are common in people of all ages and races. "The pathogenesis of inflammatory skin disease involves the release of cytokines from keratinocytes, and one of these, IL-1β, has been previously implicated in inflammatory skin disease." (PMID 23970818, 2013). "Therefore, regulating the NLRP3 inflammasome and its associated cytokines, including IL-1β, IL-18, and IL-6, is important in preventing inflammatory skin diseases." (PMID 37175425, 2023). "Several studies have shown that prolonged exposure to O3 can increase oxidative damage and promote release of pro-inflammatory cytokines, such as interleukin-1β (IL-1β) and IL-18, leading to various inflammatory skin diseases." (PMID 38393203, 2024). "UVB radiation can induce inflammatory mediators such as COX-2 and pro-inflammatory cytokines, including TNF-α, IL-6, and IL-1β, which induce the expression of NF-κB, which has been shown in inflammatory skin diseases." (PMID 38275645, 2023). "The pathogenesis of inflammatory skin disease involves the release of cytokines from keratinocytes, including interleukin (IL)-1β." (PMID 29312598, 2017). "Assessment of Ccl7, Il18, and Il1b expression is most indicative of distinguishing skin rejection from skin inflammatory disorders." (PMID 25756043, 2015). "The Nod-like receptor protein (NLRP)-3 inflammasome/IL-1β pathway is involved in the pathogenesis of various inflammatory skin diseases, but its biological role in wound healing remains to be elucidated." (PMID 25793779, 2015). "Rg5 improved inflammatory skin disorders, such as oxazolone-induced chronic dermatitis in mice, by modulating IL-1β and TNF-α production in macrophage cells and IFN-γ from Th cells." (PMID 23698769, 2013). "Furthermore, the inflammasome/IL-1β pathway is involved in the pathogenesis of various inflammatory skin diseases, and we and others have previously shown that sustained NLRP-3 inflammasome activity contributes to impaired healing in diabetic wounds." (PMID 25793779, 2015). "IL-1α and IL-1β, mainly produced by the keratinocytes in the skin, as well as TNF-α are key inflammatory cytokines in inflammatory skin diseases such as dermatomyositis and pemphigus, as well as experimental pemphigoid disease." (PMID 31001258, 2019). "Although we show only a slight reduction in IL–1β release, OSB‐specific VOCs induced a significant decrease of CCL2, a key chemokine involved in monocyte/macrophage infiltration in inflammatory skin diseases, a hint towards potential beneficial effects of OSB emissions in humans." (PMID 40114338, 2025). "When the epidermal barrier of the skin is damaged by physical or chemical stimuli, many cytokines (IL-1β, IL-6, TNF-α, IL-5, and TSLP) and chemokines (MCP-1, RNATES, TARC, MDC, CXCL8, and CXCL10) are expressed in stimulated keratinocytes to promote the progression of inflammatory skin diseases." (PMID 36670888, 2022).
leprosy (25 papers, 2010 to 2025). Leprosy is a chronic infectious disease affecting primarily the skin and peripheral nervous system. "Increased levels of IL-1β in leprosy and neural pain patients may also be associated with an analogous mechanism, wherein the increased inflammatory response maintains the nociceptive stimulus by peripheral sensitization." (PMID 32038662, 2020). "Interestingly, leprosy patients carrying a Lrrk2 missense variant are more prone to develop T1R with excessive inflammation of which IL-1β is one biomarker." (PMID 31921172, 2019). "IL-1β plays a dual role in leprosy, contributing both to mounting an antimicrobial response against M. leprae and to the acute inflammatory response and tissue damage observed in leprosy reactional episodes." (PMID 40862607, 2025). "Analysis on NLRP1 and NLPR3 inflammasomes showed significant correlations between caspase-1 and IL-1β levels in Borderline leprosy, compared to the VV and TT forms of leprosy." (PMID 37887741, 2023). "IL-8 and IL-1β are related to neutrophil recruitment and are frequently detected in the skin of leprosy patients experiencing type I reactions." (PMID 33819170, 2021). "Cytokines such as IL-1β and IL-23 induce Th17, while transforming growth factor beta and IL-10 inhibit Th17, indicating that the balance between Th17 and regulatory T cells is crucial for leprosy polarization." (PMID 37909507, 2023). "In brief, IL-1β is an independent variable related to neuropathic and nociceptive pain in patients with leprosy, and could be an important biomarker for patient follow-up." (PMID 32038662, 2020). "We also observed poor expression ofcaspase-1, IL-1β, and IL-18 in all leprosy spectrum groups." (PMID 32130367, 2020). "Our data that illustrate PGL-I/CR3 binding and NFATc translocation to generate high production of IL-1β by MPs could contribute to deciphering how excessive inflammation in severe leprosy takes place." (PMID 31921172, 2019). "Another study using single-cell and spatial sequencing approaches described the cellular architecture of leprosy granulomas and identified antimicrobial response genes in reversal reactions that were regulated by IFN-γ and IL-1β." (PMID 39283647, 2024). "Samples from leprosy patients showed down-regulation of CCL2, CCL3, CCL4 (p<0.05), while IL1β and SOD2 were borderline significant (p<0.1), confirming a repression of these genes by M. leprae ex vivo, as was observed in vitro in THP-1." (PMID 23798993, 2013). "Beside IFN-γ, also IP-10, IL-6, IL-1β, TNF-α, and MCP-1 were increased in EC from areas with high leprosy prevalence in response to these ML1601c peptides." (PMID 22363349, 2012). "We mined an independent leprosy single-cell RNA-Seq (scRNA-Seq) dataset composed of RR and L-lep skin lesions (GSE151528) and found that IL1B mRNA expression in RR lesions was restricted to myeloid cells, while TNF was expressed by both myeloid and T cells, with higher expression in myeloid cells." (PMID 40569678, 2025). "IL-1β, showed high expression in all subjects without discriminating the leprosy types in PBMC cultures." (PMID 23936569, 2013). "Furthermore, stimulation of PBMC isolated from ENL patients with TLR9 agonist led to higher levels of TNF-α, IL-6, and IL-1β, than those of non-reactional leprosy and healthy controls." (PMID 28348555, 2017). "Indeed, the increase in TNF, IL-1β, IL-6, MCP-1, and MIP-1β mediators typically produced by monocytes supports the idea of BCG-induced “trained immunity” as a Th1/Th17 heterologous mediating mechanism of immune activation favoring disease protection of HC of leprosy patients." (PMID 28467415, 2017). "Among the articles of leprosy reactions, regardless of the type of sample, IFN-γ, TNF-α, IL-6, and IL-1β were involved in T1Rs and T2Rs." (PMID 26339136, 2015).
leprosy (continued). "In this systematic review, we identified important pro- and anti-inflammatory mediators involved in the occurrence of dental infections and leprosy reactions, including IL-6, IFN-γ, TNF-α, IL-1β, IL-17, IL-10, and IL-4, which were independent of the laboratory technique and sample." (PMID 26339136, 2015).
pericarditis (25 papers, 2019 to 2025). An inflammatory process affecting the pericardium. "Therapies like Rilonacept and Goflikicept, which act against IL-1α and IL-1β, prevent the recurrence of pericarditis by inhibiting inflammation and allowing patients to discontinue corticosteroids without recurrence." (PMID 40564905, 2025). "The underway ARAMIS and RHAPSODY trials have been developed to evaluate the effectiveness of IL-1β-blocking medications in individuals diagnosed with myocarditis and concomitant pericarditis." (PMID 40284927, 2025). "There is supporting evidence from one clinical study and a number of case reports for the use of an anti-IL-1β monoclonal antibody in the management of patients with a recurrence of pericarditis." (PMID 40284927, 2025). "Rilonacept is a trap for IL-1β and has been shown in clinical trials to inhibit recurrent pericarditis episodes and prevent the recurrence of pericarditis." (PMID 38455049, 2024). "In 2021, the results on the efficacy and safety of rilonacept, an IL-1α and IL-1β cytokine trap in patients with recurrent pericarditis (≥2 recurrences), were published." (PMID 38541631, 2024). "The accumulating evidence points toa role for the NLRP3 inflammasome/IL-1β axis in the auto-inflammatoryprocess sustaining recurrent pericarditis, as outlined by a recent work." (PMID 39077487, 2023). "Of the 17 confirmed episodes of pericarditis, 14 (82.4%) occurred before establishment on prophylactic immunomodulatory therapy, 2 while on low‐dose colchicine, and 1 while on the anti‐IL‐1β monoclonal antibody canakinumab." (PMID 35658515, 2022). "Rilonacept, a soluble IL-1 receptor chimeric fusion protein neutralizing interleukin 1 alpha (IL-1α) and interleukin 1 beta (IL-1β), has demonstrated promising results in a phase II study in recurrent or refractory pericarditis." (PMID 36505131, 2022). "The therapeutic use of IL-1α and IL-1β inhibitors in patients with pericarditis has improved pain and inflammation in clinical trials." (PMID 35251049, 2022). "Canakinumab is a monoclonal antibody selectively blocking IL-1β and its use is only anecdotally reported to treat pericarditis." (PMID 32546242, 2020). "Moreover, they demonstrated increased expression of IL-1α and IL-1β in the pericardium of mouse models of pericarditis compared with controls." (PMID 41272654, 2025). "Adding to this momentum, Kiniksa Pharmaceuticals is advancing the development of KPL-387, a fully human immunoglobulin G2 (IgG2) monoclonal antibody that targets IL-1R type 1, thereby inhibiting the activity of both IL-1α and IL-1β, key drivers of inflammation in recurrent pericarditis." (PMID 41136179, 2025). "Impact of recurrent pericarditis (RP) on patient health-related quality of life (HRQoL) was evaluated through qualitative patient interviews and as an exploratory endpoint in a Phase 2 trial evaluating the efficacy and safety of rilonacept (IL-1α/IL-1β cytokine trap) to treat RP." (PMID 33882846, 2021). "Previous studies showed that IL1β can be activated by the NLRP3 inflammasome, which plays a central role in acute pericarditis clinical manifestations." (PMID 39975900, 2025). "Approved in 2008, rilonacept effectively neutralizes IL-1α and IL-1β, showing distinctive efficacy in treating CAPS and recurrent pericarditis." (PMID 41471316, 2025). "This pathway may explain colchicine’s efficacy in treating FMF and recurrent pericarditis, as it inhibits the self-assembly of cytoskeleton microtubules and reduces NLRP3-dependent IL-1β release." (PMID 39458001, 2024).